KRT25 (keratin 25)
Description:
Essential for the proper assembly of type I and type II keratin protein complexes and formation of keratin intermediate filaments in the inner root sheath (irs) (By similarity). Plays a role in the cytoskeleton organization.
Synonyms: KRT25A; ARWH3; KRT24IRS1
Tractability: No criterion of Open Targets' tractability assessment is met for any kind of drug.
Gene: Protein-coding gene on chromosome 17 (40,748,021 to 40,755,331, reverse strand). Ensembl gene ENSG00000204897.
Subcellular location: Cytoplasm
Subcellular location (Human Protein Atlas): Vesicles
Pathways (Reactome):
Developmental Biology: Formation of the cornified envelope; Keratinization
Gene Ontology:
Molecular function: protein binding; protein heterodimerization activity; structural constituent of skin epidermis; structural molecule activity
Biological process: cytoskeleton organization; hair cycle; epithelial cell differentiation; hair follicle morphogenesis; intermediate filament organization; morphogenesis of an epithelium
Cellular component: extracellular exosome; keratin filament; cytoplasm; cytoskeleton; cytosol
Genetic constraint (gnomAD): Loss-of-function variants: 34 observed, 45.11 expected, observed/expected ratio (o/e) 0.75, 90% interval 0.57 to 1. The upper end of that interval is the gene's LOEUF score, 1, which puts it in group 4 of 6, group 1 being the genes least tolerant of losing a copy. Missense variants: 501 observed, 541.44 expected, observed/expected ratio (o/e) 0.93, 90% interval 0.86 to 1. Synonymous variants: 191 observed, 205.76 expected, observed/expected ratio (o/e) 0.93, 90% interval 0.82 to 1.05.
Homologues: Orthologues: chimpanzee KRT25 (99% identical), macaque KRT25 (97% identical), dog KRT25 (93% identical), pig KRT25 (92% identical), mouse Krt25 (91% identical), rat Krt25 (90% identical), rabbit KRT25 (89% identical), guinea pig KRT25 (88% identical). Paralogues in human: KRT27 (82% identical), KRT28 (75% identical), KRT26 (71% identical), KRT10 (57% identical), KRT24 (54% identical), KRT16 (50% identical), KRT12 (49% identical), KRT14 (49% identical), KRT15 (48% identical), KRT17 (47% identical), KRT13 (45% identical), KRT9 (45% identical), and 56 more.
Diseases named in the same sentence as KRT25 in open-access papers:
KRT25 is named in the same sentence as 18 diseases in open-access papers, as found by Europe PMC text mining. Sharing a sentence is not in itself a finding about the gene and the disease. The quoted sentences say what the papers report.
hypotrichosis (6 papers, 2021 to 2025). A congenital condition, usually due to genetic aberrations, that is characterized by a lack of hair growth on the head and/or body. "In a group of patients who displayed a phenotype similar to conventional hypotrichosis but had some differences, a previously unreported homozygous mutation c.712G > T was detected within the KRT25 gene, resulting in the p.Val238Leu substitution in the K25 protein." (PMID 41426600, 2025). "Specifically, KRT75, KRT71, and KRT25 (which were found to be increased in both gene sequencing and qPCR analysis) are involved in hair and nail development, with mutations in these genes linked to conditions such as wooly hair and hypotrichosis." (PMID 40843897, 2025).
monilethrix (2 papers, 2022). Monilethrix is a rare genodermatosis characterized by a hair shaft dysplasia resulting in hypotrichosis. "Interestingly, mutations in type II hard and soft hair keratins (KRT75, KRT81,83,85,86), but not type I hair keratins (KRT25-28, KRT31-40), have reported associations with other genetic hair disorders such as Monilethrix, pseudofolliculitis barbae, and hair ectodermal dysplasia." (PMID 35145093, 2022).
hypotrichosis 8 (1 paper, 2023). Any hypotrichosis in which the cause of the disease is a mutation in the LPAR6 gene. "In addition, some paralog genes Krt25, Krt27, Krt72, Krt75, and Krt85, which also participate in the formation of keratin intermediate filaments in the IRS, could be related to Woolly Hair, Autosomal Recessive 3, and Hypotrichosis 8, which were significantly decreased in Krt71–KO mice." (PMID 37443815, 2023).
lung carcinoma (1 paper, 2021). "TUBA1C, GAPDH, KRT25, GCC2, and POTEKP were the five proteins identified as potential lung cancer-specific exosome biomarkers." (PMID 34771645, 2021).
psoriasis (1 paper, 2025). An autoimmune condition characterized by red, well-delineated plaques with silvery scales that are usually on the extensor surfaces and scalp. "Among the top 10 downregulated and top 10 upregulated DEG, we identified several key genes related to psoriasis, including Krt25, Krt8, Muc16, Slc5a7, Reg3b." (PMID 39665264, 2025).
KRT25 also shares sentences with these, for which no sentence is quoted: airway hyperresponsiveness (1 paper); anonychia congenita (1); asthma (1); childhood asthma (1); cystic fibrosis (1); ectodermal dysplasia (1); hair diseases (1); keratosis (1); osteopetrosis (1); Pseudofolliculitis barbae (1); skin inflammation (1); staphylococcus aureus infection (1); Woolly hair (1).